USP22 (ubiquitin specific peptidase 22)
Diseases named in the same sentence as USP22 in open-access papers (continued):
Sharing a sentence is not in itself a finding about the gene and the disease.
hepatocellular carcinoma (continued). "Also, USP22 is responsible for hepatocellular carcinoma migration." (PMID 33123271, 2020). "In hepatocellular carcinoma, USP22 expression increases via PRDM1, leading to diminished SPI1 degradation through USP22 upregulation." (PMID 38566199, 2024). "DUBs, including USP14, USP22, and USP29, mediate the deubiquitylation and stabilization of HIF-1α, promoting self-renewal ability and drug resistance in hepatocellular carcinoma." (PMID 36694209, 2023). "USP22 can also affect the transcription of the phosphatase DUSP1 by E2F6 protein through deubiquitination, which can activate the AKT pathway in hepatoma cells." (PMID 35875077, 2022). "Moreover, immunofluorescent staining was conducted, revealing the co‐localisation of USP22 and CDK11B in hepatocellular carcinoma cells." (PMID 40341781, 2025). "USP22 deubiquitinates and enhances the stability of PPARγ protein, thereby promoting the synthesis of FASN, ACLY, and ACACA, and facilitating the malignant progression of hepatocellular carcinoma." (PMID 39944823, 2025). "In addition, USP22 was shown to sustain the glycolytic capacity in BLBC and particularly under hypoxic conditions in hepatocellular carcinoma." (PMID 38347585, 2024). "USP22 stabilizes COX2 protein, thereby promoting the proliferation of hepatoma cells." (PMID 35935969, 2022). "In addition, USP22 can directly interact with SIRT1 and regulate the protein expression level of SIRT1, which promotes the resistance of hepatoma cells to 5-fluorouracil (5-FU)." (PMID 35875077, 2022). "Meanwhile, EZH2, another Polycomb-group (PcG) protein associated with histone modification of H3K27me3, showed no change in abundance, consistent with a study reporting that USP22 silencing did not change EZH2 in hepatocellular carcinoma." (PMID 28415621, 2017). "However, there has been a lack of thorough investigation into the role of USP22 in hepatocellular carcinoma development and Sorafenib resistance." (PMID 40341781, 2025). "Moreover, USP22 directly interacts with sirtuin 1 (SIRT1) and positively regulates SIRT1 protein expression, leading to activation of the SIRT1/AKT/ABCC1 pathway and MDR of hepatocellular carcinoma." (PMID 36694209, 2023). "For example, USP22 can stabilize the E2F6 stability and activate Akt pathway in hepatocellular carcinoma (HCC), leading to aggressive progression of HCC." (PMID 35692754, 2022). "In addition, USP22 may induce autophagy through deubiquitination of SIRT1, thereby reducing the sensitivity of hepatoma cells to chemotherapeutic drugs." (PMID 35935969, 2022). "Additionally, USP22 downregulates transferrin receptor (TFRC) transcription by removing H2B lysine 120 ubiquitination (H2BK120ub) from TFRC transcription start site (TSS) downstream region, thereby inhibiting Sorafenib‐induced ferroptosis in hepatocellular carcinoma." (PMID 40341781, 2025). "USP22 is an identified oncoprotein that is highly expressed in hepatocellular carcinoma (HCC) but not in other types of cancer." (PMID 36176401, 2022). "Moreover, the expression of lncRNA HULC, regulated by miR-6825-5p, miR-6845-5p, and miR-6886-3p, elevates the deubiquitination effect of USP22 on SIRT1, making hepatocellular carcinoma (HCC) cells resistant to oxaliplatin and inducing protective autophagy in HCC cells." (PMID 38702734, 2024). "Notably, upregulation of USP22 increases ABCC1 expression and subsequently contributes to sorafenib resistance in hepatocellular carcinoma (HCC) cells, suggesting that USP22 may serve as a therapeutic target for surmounting sorafenib resistance." (PMID 36694209, 2023).
colorectal cancer (42 papers, 2011 to 2025). A primary or metastatic malignant neoplasm that affects the colon or rectum. "USP22 is frequently overexpressed in breast, colon, lung, and other cancers, and overexpressed USP22 is associated with chemotherapy resistance in hepatocellular, breast, and colorectal cancers." (PMID 37946202, 2023). "Overexpressed USP22 is associated with chemotherapy resistance in hepatocellular, breast, and colorectal cancers." (PMID 36123698, 2022). "By analyzing 192 colorectal cancer patients, it was found that the expression of USP22 was associated with the occurrence of CRC metastasis and the increased chance of chemotherapy resistance." (PMID 35935969, 2022). "In breast and colorectal cancer, upregulation of USP22 was reported to be associated with decreased therapeutic efficacy of the HSP90 inhibitor ganetespib." (PMID 34660907, 2020). "USP22 was also identified as an oncogene and associated with many cancers, such as colorectal cancer, breast cancer, oral squamous cell carcinoma, anaplastic thyroid carcinoma, glioma and GC." (PMID 28415621, 2017). "Among the putative miR-143 targets we also found the deubiquitinating enzyme USP22, which have been reported to be associated with a poor prognosis of colorectal cancer and invasive breast cancer." (PMID 22691140, 2012). "USP22 is overexpressed in colorectal cancer and its activation is associated with tumor progression and therapy failure." (PMID 21283576, 2011). "Importantly, while loss of USP22 expression resulted in increased tumor growth and aggressiveness, activation of the mTOR pathway resulted in a synthetic vulnerability of USP22-deficient colorectal cancer cells to mTOR inhibitor treatment." (PMID 31801945, 2019). "In colorectal cancer, USP22 expression was negatively correlated with tumor purity, which was an indicator of prognosis, as determined by analyzing the ratio of stromal and infiltrated immune cells (r = −0.14, p = 4.55×10−3, Spearman)." (PMID 38520088, 2024). "Conversely, USP22 has been demonstrated to exert an anticancer effect on colorectal cancer by diminishing mTOR activity." (PMID 39143031, 2024). "USP22 has been reported to play an oncogenic role and indicate poor prognosis in various human cancers including gastric, breast and colorectal cancers." (PMID 38784391, 2024). "Colorectal carcinomas represent tumor entities in which USP22 expression is well correlated with malignant tumor progression." (PMID 38467608, 2024). "USP22 acts as an oncogene in colorectal cancer by activating BMI1, which, in turn, activates the INK4a/ARF pathway and Akt signaling pathway." (PMID 35935969, 2022). "It has been shown that USP22 is overexpressed in many solid tumors, for example, bladder cancer, breast cancer and colorectal cancer, which means that it is a potential cancer biomarker." (PMID 35784926, 2022). "USP22 plays an important role in the progression of colorectal cancer by interfering with cell cycle progression." (PMID 35935969, 2022). "Exosomal lncRNA KCNQ1OT1 derived from colorectal cancer cells promotes colorectal cancer immune escape through miR-30a-5p/USP22 regulated PD-L1 ubiquitination." (PMID 36358833, 2022). "The expression of USP22 increased from normal mucosa to colorectal cancer and was also significantly increased from adenoma to colorectal cancer." (PMID 35935969, 2022). "This suggests that USP22/Wnt/β-catenin signaling can mediate 5-FU resistance in colorectal cancer cells." (PMID 35935969, 2022). "Drug resistance suppressed by miR-30-5p in colorectal cancer cells is partially abolished by USP22 overexpression." (PMID 35935969, 2022).
colorectal cancer (continued). "USP22 overexpression has been reported in several human cancers such as bladder cancer, colorectal cancer and oral squamous cell carcinoma and is related to the clinicopathological parameters and prognosis of many types of cancers." (PMID 35784926, 2022). "Together, these results suggest that FASN is stabilized by USP22 in colorectal cancer, and the dysregulated USP22/FASN axis is a important driver for tumorigenesis." (PMID 36333288, 2022). "Studies have found that USP22 plays a tumor suppressor function in colorectal cancer by reducing mTOR activity." (PMID 35935969, 2022). "It was shown that a promoter region from − 210 to + 52 contains the basal promoter activity of USP22 in colorectal cancer Hela cell." (PMID 36123698, 2022). "Deletion of Usp22 in human colorectal cancer cell lines increased tumorigenic phenotypes and increased mTOR activity." (PMID 34503086, 2021). "Our previous studies demonstrated a function for USP22 in intestine epithelial cell differentiation in vivo and a surprising tumor-suppressive function for USP22 in colorectal cancer." (PMID 34007022, 2021). "USP22 is also upregulated in many cancer cells and activates the proliferation, migration, and invasion of gastric cancer, colorectal cancer, and breast cancer." (PMID 33664230, 2021). "USP22-dependent HSP90AB1 expression contributed to resistance to HSP90 suppression in colorectal cancer." (PMID 34753387, 2021). "In contrast to these pro-oncogenic functions of Usp22, a recent study indicated that Usp22 shows a context-dependent tumor suppressor function in colorectal cancer." (PMID 34503086, 2021). "USP22 controls secreted protein acidic and rich in cysteine expression and inflammation intensity in colorectal cancer." (PMID 34753387, 2021). "Depletion of USP22 in an in vivo model of colorectal cancer was shown to increase the therapeutic potentiation of ganetespib." (PMID 34660907, 2020). "USP22 promotes cell proliferation, migration, and invasion in multiple cancers, including glioma, lung adenocarcinoma, thyroid carcinoma, colorectal cancer, and gastric cancer." (PMID 32063746, 2020). "For example, USP22 expression was significantly increased in primary colorectal carcinoma tissues relative to matched normal adjacent tissues at the protein and mRNA level." (PMID 29210986, 2017). "In colorectal carcinoma, USP22 promoted cell proliferation by activating BMI1-mediated INK4a/ARF pathway and Akt pathway." (PMID 28415621, 2017). "In particular, a role of USP22 has been suggested in non-small cell lung cancer, gastric carcinoma, glioma, pancreatic cancer, breast and colorectal cancer." (PMID 26431380, 2015). "USP22 was also reported to control cell cycle progression since its depletion resulted in the induction of a G1 cell cycle arrest in colorectal cancer cells in vitro." (PMID 26431380, 2015). "Additionally, previous studies in colorectal cancer and gastric cancer have observed decreased total β-catenin levels upon inhibition of USP22." (PMID 38370338, 2024). "Inhibitors of EZH2 can activate the expression of deubiquitinase USP22 in colorectal cancer via canonical epigenetic regulation through H3K27me3, thereby stabilizing PD‐L1 protein and enhancing its expression, inducing immune evasion and diminishing the anti‐tumor therapeutic efficacy." (PMID 38520088, 2024).
colorectal cancer (continued). "USP22 increases AP4 transcription to induce EMT in colorectal cancer, which may induce tumor metastasis." (PMID 35935969, 2022). "USP22 is abnormally expressed in various malignant tumors such as prostate cancer, lung cancer, liver cancer, and colorectal cancer, which suggests that USP22 may play an important role in tumors." (PMID 35935969, 2022). "In addition, multiple studies have shown that USP22 can promote colorectal cancer stemness through the Wnt/β-catenin pathway." (PMID 35935969, 2022). "Furthermore, we found that c-Myc overexpression significantly upregulated both USP22 promoter-driven luciferase activity and USP22 protein levels in two lung cancer cells (A549, H1299) and a colorectal cancer cell line HCT116." (PMID 36123698, 2022). "Contradictory functions of USP22 in the development of colorectal cancer have been reported." (PMID 34660907, 2020). "Together, in this study we demonstrate that the constitutively expressed heat shock factor HSP90AB1 is highly dependent upon USP22-mediated epigenetic regulation in human breast and colorectal cancer cell lines as well as in murine mammary and colorectal tumors." (PMID 31801945, 2019). "Moreover, high-level USP22 predicted worse overall and disease-free survivals in colorectal cancer." (PMID 36333288, 2022). "It should be noted that USP22 may have a bidirectional function in colorectal cancer." (PMID 35935969, 2022). "In colorectal cancer, USP22 may induce chemoresistance through the Wnt/β-catenin signaling pathway." (PMID 35935969, 2022). "Despite the key role USP22 plays in many types of tumours, evidence for its involvement in CCA development is completely absent and its dichotomous association with different types of tumours—high USP22 expression stimulates breast tumour growth, whereas impedes colorectal cancer development." (PMID 34226501, 2021). "Moreover, our findings may contribute to recent results by Kosinsky and colleagues identifying a tumor suppressor function for USP22 within a colorectal cancer context." (PMID 33801331, 2021). "In addition, positive USP22 IHC labeling in primary colorectal carcinoma was associated with a reduced five-year disease-free survival rate (26%) compared to USP22-negative cancers (71%)." (PMID 29210986, 2017). "The ROS-mediated inhibition of USP22 is relieved, leading to the stabilization of FASN, thereby promoting lipid synthesis and colorectal cancer growth." (PMID 39944823, 2025). "The expressions of USP22 and BMI1 are closely related in various cancer tissues, such as liver cancer, colorectal cancer, and gastric cancer." (PMID 35935969, 2022). "As a member of the 11-gene “death-from-cancer” gene expression signature, ubiquitin-specific protease 22 (USP22) has been considered an oncogene in various human malignancies, including colorectal cancer (CRC)." (PMID 33920268, 2021). "USP22 acts as a major transcriptional factor to regulate major vault protein (MVP) drug resistant gene and links to chemotherapeutic failure in colorectal cancer." (PMID 28567015, 2017). "Ubiquitin specific peptidase 22 (USP22), a putative cancer stem cell marker, is overexpressed in liver metastases of colorectal cancer (CRC)." (PMID 28427243, 2017). "USP22 regulates cell-cycle progression via both INK4a/ARF pathway and Akt signaling pathway in human colorectal cancer." (PMID 24466336, 2014). "Mainly USP4, USP7, USP22, UCHL1, UCHL5, and OTUB1 could be used as biomarkers for each type of cancer such as EOC, breast cancer, melanoma, cervical cancer, and colorectal cancer." (PMID 37107644, 2023).
colorectal cancer (continued). "All these results illustrated the pro-tumorigenic effects of RNF220/USP22/BMI1 signal pathway on proliferation and stemness of colorectal cancer, providing novel insights into RNF220 as clinical therapeutic candidates for future drug design and development targeting colorectal cancer." (PMID 34753387, 2021). "The tumor-promoting effect of lncRNA KCNQ1OT1 was through the autocrine effect of tumor cell-derived exosomes, which mediates the miR-30a-5p/USP22 pathway to regulate the ubiquitination of PD-L1 and inhibits CD8+ T-cell response, thereby promoting colorectal cancer development." (PMID 34350172, 2021). "Our study discovered USP22 combined with BMI1, and thus accelerating stemness of colorectal cancer." (PMID 34753387, 2021). "Our findings establish that the USP22-FASN axis plays an important role in regulating lipid accumulation and colorectal tumorigenesis, and targeting this axis may represent a promising therapeutic strategy for colorectal cancer." (PMID 36333288, 2022). "USP22-depleted tumor cells exhibited a high sensitivity to HSP90 inhibitor ganetespib, suggesting that targeting USP22 and HSP90β may prove effective for the treatment of breast and colorectal cancer." (PMID 35127545, 2022). "However, the functions of USP22 in colorectal cancer have not been investigated." (PMID 34753387, 2021). "Another study unexpectedly demonstrated that ablation of USP22 leads to a reduction, rather than an increase, in global H2bub1 levels in HEK 293 T and H116 colorectal cancer cells." (PMID 31842906, 2019).